DUSP6 (dual specificity phosphatase 6)
Diseases named in the same sentence as DUSP6 in open-access papers (continued):
Sharing a sentence is not in itself a finding about the gene and the disease.
cancer (continued). "Thereby identification of DUSP6 targeting as a novel approach for HER3 inhibition may have broad ramifications in different combination therapy settings across different cancer types." (PMID 38886591, 2024). "ERK-independent anti-apoptotic activity for DUSP6 in cancer cells was suggested also recently." (PMID 38886591, 2024). "If this resilience does not work properly, hPSCs could be spontaneously transformed into cancer cells with a tilted differentiation propensity, as observed in DUSP6 KO-A cells." (PMID 37029196, 2023). "In addition, a previous study has confirmed that DUSP6 can serve as an oncogene and has anti-cancer effects." (PMID 35630630, 2022). "Thus, ACA-28 induced DUSP6 downregulation in cancer cells with highly active ERK, thereby inducing ERK hyperphosphorylation and cell death." (PMID 34685488, 2021). "CSCs are also responsible for cancer progression and metastasis, and we examined whether DUSP6 promotes these activities." (PMID 32159851, 2020). "Several reports reveal a role for DUSP6 in development, organogenesis, and cancer." (PMID 30941033, 2019). "In contrast, two recent reports contain evidence that DUSP6/MKP-3 may actually be an oncogenic driver in certain human cancers." (PMID 30401534, 2019). "Targeting DUSP6 or other negative regulators might offer a treatment strategy for certain cancers by inducing the toxic effects of RAS-mediated signaling." (PMID 30475204, 2018). "The reduced expression of DUSP6 in cancer cells might be due to the acceleration of this degradation system, which is indeed the case in ovarian cancer cells." (PMID 25699241, 2015). "In various types of cancer, DUSP6 acts in a contradictory manner." (PMID 24260056, 2013). "However, recent studies indicate that at least some cancer relevant DUSP6 functions may by ERK-independent." (PMID 38886591, 2024). "In addition, future studies should examine the nuclear interaction partners of DUSP6 along with the epigenetic machinery that DUSP6 may regulate in cancer biology as well as the underpinning gene signatures associated with DUSP6 in brain metastases." (PMID 31238530, 2019). "In addition to the enrichment of guides targeting TM9SF2, LAPTM4A, and genes related to sphingolipid biosynthesis, our analysis detected enrichment for guides targeting several genes associated with cancer and cell proliferation (MLLT3, TFAP4, ZNF217, and DUSP6) (35, –, 38)." (PMID 29921669, 2018). "Our results showed that genes CACNG6, DUSP6 and MAP4K3 in the MAPK pathway have reorganized spatial structures in MM, and associate with gene expression regulation as well as epigenetic mark changes, which might contribute to cancer development." (PMID 29203764, 2017). "However, DUSP6 is overexpressed and acts as an oncogene in certain other types of cancer." (PMID 24260056, 2013). "At variance with this study, other authors showed that DUSP6 KD resulted in increased ERK1/2 activity, cell proliferation rate, anchorage-independent growth ability, and resistance to cisplatin in the same cancer model." (PMID 40943262, 2025). "BCI is a semi-allosteric inhibitor of both DUSP1 and DUSP6 and several studies have demonstrated that BCI phenocopies genetic DUSP6 inhibition in cancer." (PMID 38886591, 2024). "Clinically DUSP6 and HER3 mRNA expression also correlated in HER2+ cancer samples in the TCGA-BRCA dataset." (PMID 38886591, 2024). "Out of the eight cancer-related genes, we identified that pleural fluid GRB2, WEE1, RNF4, and DUSP6 mRNA levels were significantly different between patients with MPE and benign PE by using two-independent sample t-tests." (PMID 37095178, 2023). "In contrast, dual inactivation of DUSP4 and DUSP6 selectively impairs growth in NRAS and BRAF mutant cells in cancer through hyperactivation of MAPK signaling." (PMID 37026010, 2023). "Thus, DUSP6 may increase the population of cancer cells in the quiescent state." (PMID 32159851, 2020).
cancer (continued). "In common with the cytoplasmic ERK-specific phosphatase DUSP6/MKP-3 (see Section 3.1.3), elevated DUSP5 expression is observed in a range of Ras or Braf mutant cancer cells where it is presumed to suppress oncogenic ERK activation." (PMID 30401534, 2019). "The best characterized DUSP6 inhibitor molecule BCI ((E)-2-Benzylidene-3-(cyclohexylamino)-2,3-dihydro-1H-inden-1-one), is a semi-allosteric inhibitor of both DUSP1 and 6 that phenocopies genetic DUSP6 inhibition in several cancer models." (PMID 38886591, 2024). "Interestingly, DUSP6 was identified as hub genes and anti-cancer compounds can be developed by inhibiting the interaction of ERK2 and DUSP6." (PMID 38418476, 2024). "The protein subnetwork of PIK3R2 could be used for further pan-cancer studies in the future: DUSP10, DUSP6, FHL2, IRS2, PIK3R2, and RIPK2." (PMID 36329531, 2022). "Altogether, compounds targeting negative regulators of the ERK cascade, such as DUSP6 and SPRY proteins, might offer a treatment strategy for certain cancers by inducing the toxic effects of RAS-mediated hyperactive ERK signaling." (PMID 34685488, 2021). "Interestingly, when we investigated a purely NRAS-dependent murine cancer cell line, we observed a much higher baseline level of DUSP4 and DUSP6 compared to its dual NRAS and AKT-addicted counterpart, which is suggestive of a certain exclusivity towards the RAS oncogenic pathway." (PMID 37946160, 2023). "However, the KEGG pathway “Transcriptional misregulation in cancer” were represented with four genes mapping to the pathway (Bcl6, Zbtb16, Aff1, and Dusp6), but not significant (adj." (PMID 34428250, 2021). "This early response of DUSP6 to ERK activation could explain the apparently contradictory activation of ERK by HE4 in cancer cells and our current results here showing HE4 upregulation of DUSP6 expression leading to suppression of ERK phosphorylation in PBMC subsets." (PMID 30941033, 2019). "For example, DUSP6 as a phosphatase, regulated phosphorylation of its downstream gene ERK1/2 to promote cell proliferation, and it may contribute to the relapse by crosstalk with WT1 through transcriptional misregulation in cancer pathway." (PMID 30195757, 2018).
infection (9 papers, 2011 to 2024). The state of being infected such as from the introduction of a foreign agent such as serum, vaccine, antigenic substance or organism. "DUSP6 expression plasmid co-infection, however, prevented the aggressive behavior brought on by SKA1 overexpression in ccRCC cells." (PMID 36462498, 2022). "In Vero cells, DUSP6 mRNA gradually increased over infection time from 4 to 20 hpi; in H1299 cells, DUSP6 mRNA was induced at 4 hpi, peaked at 8 hpi, and decreased over infection time from 8 to 20 hpi." (PMID 33431056, 2021). "DUSP1, IL-24, and DUSP6 were induced 2–3 hours post-infection with the high dose of wild-type C. albicans and reached a maximal level of induction ~6 hours post-infection." (PMID 27088599, 2016). "Two hours post-infection cell numbers among the wild-type, rim101Δ/Δ, and efg1Δ/Δ cph1Δ/Δ strains are similar, yet epithelial cells induced DUSP6 only in response to wild-type C. albicans." (PMID 27088599, 2016). "To identify that the regulatory function of ALV-miR-p19-01 on viral replication was regulation of DUSP6 expression, we transfected ALV-miR-p19-01 mimics into DF-1 cells, followed by infection with ALV-J rSCAU1903-mut." (PMID 35458535, 2022). "To investigate the effect of DUSP6 on ALV-J replication, we constructed an eukaryotic expression plasmid pRK5-flag-DUSP6, and transfected it into DF-1 cells, followed by infection with ALV-J rSCAU1903-mut." (PMID 35458535, 2022). "Consistent with a previous report, genes in the DUSP family (DUSP1, DUSP2, DUSP5 and DUSP6), which regulate MAPK signaling, were down-regulated at four time points post-infection." (PMID 23527143, 2013).
cardiovascular diseases (3 papers, 2021 to 2024). "Additionally, several Dox_H3K27ac-upregulated genes including Egr-1, Adam17, Dusp6, Ddit4 and Angptl4 might potentially contribute to Dox-induced cardiotoxicity, since they have been proved to be associated with the progression of cardiovascular disease." (PMID 39014511, 2024).
neurodegenerative disease (2 papers, 2019 to 2024). A disorder of the central nervous system characterized by gradual and progressive loss of neural tissue and neurologic function. "It is not surprising to find striking changes in the expression levels and activity of these phosphatases in neurodegenerative diseases, as occurs with the downregulation of DUSP1 and DUSP6 in AD and HD." (PMID 31018603, 2019).
metabolic disease (1 paper, 2017). A congenital disorder (due to inherited enzyme abnormality) or acquired (due to failure of a metabolically important organ) disorder resulting from an abnormal metabolic process. "Future studies should clarify this potential role of the genetic background, of the diet, and of host microbiome interactions for DUSP6-ERK signaling and the susceptibility for DIO and etiology of metabolic disease." (PMID 28873424, 2017).
DUSP6 also shares sentences with these, for which no sentence is quoted: endometriosis (2 papers); Hyperglycemia (2); Hypoglycemia (2); inflammatory bowel disease (2); Insulin resistance (2); Lung Squamous Cell Carcinoma (2); acute kidney injury (1); acute leukemia (1); asthma (1); autism (1); Autoimmunity (1); cardiac arrest (1); celiac disease (1); congenital hypogonadotropic hypogonadism (1); dyslipidemia (1); end stage renal disease (1); endometrial adenocarcinoma (1); endothelial dysfunction (1); esophageal carcinoma (1); gastric tumors (1); gastrointestinal tumors (1); hematopoietic cancers (1); hemorrhage (1); Hernia (1); Huntington disease (1); hypertensive heart disease (1); hypogonadism (1); infarction (1); injury (1); ischemic stroke (1).
A further 20 diseases each share a sentence with DUSP6 in 1 paper.